ENG (endoglin)
Diseases named in the same sentence as ENG in open-access papers (continued):
Sharing a sentence is not in itself a finding about the gene and the disease.
tumor (continued). "Thus, it can be seen that ENG plays a crucial role in RSVL-promoted tumor microvessel growth, of which the expression levels of ENG are negatively correlated with tubule network formations in the HCC827-HUVEC co-culture model." (PMID 32326402, 2020). "Interestingly, the integral membrane protein endoglin (CD105) also conveys characteristic features of a potent tumor stromal marker for cancer imaging and therapy." (PMID 32316521, 2020). "Most widely recognized RCC-CSCs biomarker - endoglin that is CD105 - surface expression is to be distinctive for these cells, and within the tumor only a small subpopulation is expected to express this protein, as CSCs usually represent minor fraction of the total tumor mass." (PMID 32214151, 2020). "Another subset of circulating and tumor-associated monocytes endowed with proangiogenic activity, are characterized by the expression of the TIE-2/Tek angiopoietin receptor, Endoglin and VEGF-R2 in the intermediate monocytes subset (moM2, CD14++/CD16+) as confirmed by a genomic analysis." (PMID 33108409, 2020). "In addition, treatment with the anti-endoglin monoclonal antibody TRC105 or with different anti-endoglin shRNAs, siRNAs or miRNAs reduces tumor growth through the reduction of blood vessels inside the tumor." (PMID 31897911, 2020). "However, hematoxylin/eosin staining showed that the vessels inside the tumors developed in ENG+ mice were even more impaired and leaky than those that developed in WT mice, resulting in increased blood extravasation, blood islets and tumor edema." (PMID 31897911, 2020). "Therefore, Endoglin expression changes in the tumor and in the vascular endothelium, modulating malignancy." (PMID 32434528, 2020). "Mouse tumor models deprived of endoglin, a co‐receptor for TGF‐β in endothelial cells, exhibited increased metastatic ability accompanied by the EndMT, suggesting that elevated vascular permeability during this process allows extravasation and intravasation of tumor cells." (PMID 31094056, 2019). "Thus, the endoglin (CD105) has drawn a lot of attention as a novel alternative biomarker for the tumor diagnosis, prognosis, and therapy." (PMID 30498402, 2018). "It is worth noting that increased endoglin expression can be observed in proliferating tumour ECs, with only small expression in resting ECs, which might be an advantage in the choice of anti-endoglin therapy." (PMID 30563158, 2018). "Our results show that the combination of endoglin-based DNA vaccine with IL-12 repolarizes TAMs phenotype from M2-like (tumor growth-promoting) into M1-like (tumor growth-inhibiting) which affects the structure of tumor blood vessels and tumor regression." (PMID 29320562, 2018). "High expression of endoglin in non-tumour tissue suggests that this microenvironment might play an especially important role in the progression of HCC." (PMID 30563158, 2018). "The molecular mechanisms of HCC involving endoglin described in the literature connect this marker with both tumour angiogenesis and liver fibrosis, while the autocrine/paracrine mechanisms of action of endoglin, produced by tumour cells, are poorly recognized." (PMID 30563158, 2018). "Due to the observation that endoglin (CD105) is selectively expressed (or overexpressed) in activated vascular ECs in tumours (including HCC), it was hypothesized that it can also be a useful target for vascular-targeted anti-angiogenic therapy." (PMID 30563158, 2018). "This form of endoglin in tumours serves as a marker of poor prognosis." (PMID 30563158, 2018). "In HCC-associated angiogenesis in vivo, endoglin expression mainly concerns tumour ECs (TECs), activated ECs in adjacent non-tumour area, and different non-endothelial cells (e.g., hepatic stellate cells)." (PMID 30563158, 2018). "HCC tumour SMMC7721-GFP xenograft-bearing mice were treated with 131I-anti-endoglin mAb." (PMID 30563158, 2018). "Playing a role in tumor angiogenesis, endoglin can be used in diagnosis, prognosis, and therapy." (PMID 29276515, 2017).
tumor (continued). "Molecular biology studies have indicated that at least regarding Endoglin (HHT1) reduced levels may reflect reduced tumour angiogenesis." (PMID 27876060, 2016). "Also, it is still unclear what role BMP9, the most prominent ligand for both ALK1 and endoglin, plays in the regulation of tumor angiogenesis through its receptors." (PMID 27741515, 2016). "Furthermore, the current study indicates dual targeting of ALK1 and endoglin as a promising additional possibility for combinatorial targeting of neoangiogenesis and tumor growth." (PMID 27741515, 2016). "Tumour xenografts treated with anti-endoglin monoclonal antibodies showed anti-angiogenic effects which could be enhanced with chemotherapy, this antibody was used to create a human chimeric antibody named TRC105." (PMID 26620208, 2016). "Furthermore, we have utilized mice deficient for BMP9 (gene name Gdf2) to investigate the impact of ligand binding to ALK1 and endoglin on tumor parameters." (PMID 27741515, 2016). "Therefore, it is involved in the development of tumor vasculature through promoting angiogenesis and the targeting of endoglin with antibodies resulted in an anti-tumor effect and a reduced number of blood vessels." (PMID 26712792, 2015). "Moreover, in our recent studies, endoglin downregulation was shown to have an anti-tumor effect mediated by vascular targeted action, which was both anti-angiogenic and vascular disrupting." (PMID 26712792, 2015). "Higher endoglin expression in the B16F10 tumor model could also reflect higher vascularization of B16F10 tumors and this could further enhance the anti-tumor effect in B16F10 tumors." (PMID 26712792, 2015). "However, the opposite was observed in vivo in tumors, where there was a higher expression of endoglin and better anti-tumor effectiveness in the B16F10 tumor." (PMID 26712792, 2015). "Another promising candidate target against tumor endothelium is endoglin or CD105." (PMID 26636036, 2015). "However, the function of soluble endoglin in carcinogenesis is still debated, though an antiangiogenic role in the tumour microenvironment was suggested, based on its in vitro capability of reducing both spontaneous and VEGF-induced angiogenesis." (PMID 26296972, 2015). "Endoglin is an integral cell membrane receptor located on proliferating endothelial cells, whereas VEGF is a soluble angiogenic factor that is primarily released by tumor cells and tumor-associated stromal cells." (PMID 24994097, 2014). "At the molecular level, we noted a recurrent overlap between the AngioSwitch signature and several cellular signaling pathways that have been functionally implicated in RIP1-Tag2 tumor progression, including the PDGF receptor β and its ligand PDGF-BB or endoglin." (PMID 25301723, 2014). "ENG (CD105) is a membrane protein overexpressed in tumor-associated endothelial cells and is a marker of proliferating endothelial cells and surrogate for tumor angiogenesis." (PMID 24999452, 2014). "Moreover, soluble ENG has been shown to inhibit tumor angiogenesis, and elevated placental expression of ENG results in high serum levels of soluble ENG that contribute to vascular dysfunction in pre-eclampsia." (PMID 24489709, 2014). "In TS/A tumor cells the expression of endoglin was very low." (PMID 23593103, 2013). "Endoglin in the blood vessel endothelium is involved in the control of cell proliferation, migration and capillary tube formation, and plays a pro-angiogenic role in tumor development." (PMID 22929622, 2012). "In the present study, we examined whether toxicarioside A, a cardenolide isolated from Antiaris toxicaria, could inhibit tumor growth and its relationship with the endoglin." (PMID 23209720, 2012).
tumor (continued). "In addition, endoglin expression was also detected in situ in the tumor vessels by immunofluorescence." (PMID 23209720, 2012). "Endoglin was detected in the cytoplasm and on the membrane of tumor and vascular cells." (PMID 23088614, 2012). "Considering that TGF-β is one of the endoglin's ligands, we investigated whether HUVECs or tumor cells could express TGF-β and whether toxicarioside A would affect TGF-β expression." (PMID 23209720, 2012). "Therefore, it is easy to conceive that the TGF-β secreted by the tumor cells will act with the endoglin in the endothelial cells to promote tumor angiogenesis, which will further facilitate tumor growth and metastasis." (PMID 23209720, 2012). "In addition, endoglin expression was decreased in tumor tissues treated with toxicarioside A and in vitro cultured HUVEC supplemented with toxicarioside A in the culture media, but not in CT26 and LL/2 tumor cells." (PMID 23209720, 2012). "In addition, recent studies on human and experimental models of carcinogenesis point to an important tumor cell–autonomous role of endoglin by regulating proliferation, migration, invasion, and metastasis." (PMID 21170488, 2010). "Since activation of TGF‐β signaling augments TGF‐β production, generating a self‐stimulating autocrine signaling loop in myCAFs during tumor progression, we reasoned that ENG expression may be required for maintenance of TGF‐β autocrine signaling in these cells." (PMID 40644310, 2025). "Since our previous work indicated that TGF‐β signaling becomes stably activated in myCAFs during tumor progression, we speculated that the dysregulated expression of ENG, a TGF‐β superfamily coreceptor, may be involved in TGF‐β signaling activation in these fibroblasts." (PMID 40644310, 2025). "Therefore, this increased ENG expression may have the potential to serve as a therapeutic target for tumor‐ and metastasis‐promoting myCAFs." (PMID 40644310, 2025). "Moreover, ENG might be a novel target for tumor immune response and immunotherapy in pancancer, including BC." (PMID 39247590, 2024). "We assumed that ENG might be a novel target for tumor immune response and immunotherapy." (PMID 39247590, 2024). "HCC tumor tissue contains abundant microvessels, and tumor cells might express ENG protein to promote intertumoral angiogenesis, which will promote intrahepatic and extrahepatic metastasis of the tumor and presumably bring a worse prognosis, but further trials are needed." (PMID 37907783, 2023). "All these data suggest that endoglin might be an excellent marker of tumor vascularization." (PMID 36844233, 2023). "Similarly, increases in tumor cell endoglin levels in shINHA tumors in vivo may reflect compensatory responses to changes in inhibin expression consistent with recent reports on endoglin expression changes in ovarian cancers." (PMID 35654828, 2022). "One study suggested that toxicarioside A could hinder tumor development via endoglin." (PMID 35409247, 2022). "In addition to vascularization, endoglin-based imaging could allow for precise image-guided resections, upon identification of specific tumor types that express endoglin beyond the endothelium or are highly vascularized." (PMID 33946583, 2021). "Finally, we, will present endoglin as a key protein in the formation of a more immunosuppressive tumor microenvironment and, therefore, as a possible biomarker of this type of TME and a possible therapeutic target to, through vascular normalization, generate a more immunosupportive TME." (PMID 33800564, 2021). "Additionally, targeting of B7-H3, Mac-1 and Endoglin (mAb25, mAb26, and mAb27) has been reported to polarize TAMs from their common, pro-tumorigenic (“M2”) state towards an anti-tumorigenic (“M1”) state, potentially enhancing anti-tumor immune responses." (PMID 33627649, 2021).
tumor (continued). "Therefore, the normalization of the vasculature resulting from the administration of anti-endoglin therapies may reduce tumor cell intravasation and increase the effectiveness of chemotherapy, as has already been observed with anti-VEGF and ALK1-Fc treatments." (PMID 31897911, 2020). "Moreover, endoglin knockdown in these tumor cells reduces invasiveness and growth." (PMID 32059544, 2020). "However, according to our model and our results, the poor prognosis associated with high levels of endoglin is not related to a greater number of vessels or a larger tumor size." (PMID 31897911, 2020). "Indeed, the recent studies indicate that targeting ENG suppresses tumor angiogenesis." (PMID 29484142, 2018). "In future research joining the fields of basic sciences and biotechnology, it could be worth analysing the EC progenitors in the liver or determining more precisely of the roles of other cells that synthesise endoglin in hepatocarcinogenesis (including tumour cells)." (PMID 30563158, 2018). "This might be linked to the more important role of that glycoprotein in initial phases of HCC angiogenesis, in which endothelial sprouting occurs due to hypoxia and acidosis of the tumour microenvironment, which causes overexpression of HIF-1α and activation of endoglin gene promoter." (PMID 30563158, 2018). "The divergent results on tumor parameters following targeting of ALK1 or endoglin, both thought to act in concert in the same endothelial cell regulatory pathway, begs the questions of which signaling event is dominant and whether combinatorial targeting would be beneficial." (PMID 27741515, 2016). "The analysis of larger patient groups would be necessary to establish the robustness of the correlations found in this study and would especially be interesting to assess whether high endoglin expression significantly correlates to a high tumor vascularization and to a low metastasis-free survival." (PMID 23088614, 2012). "Besides the commonly used panendothelial markers such as CD31, CD34, Factor VIII, endoglin (CD105) has been proposed as a marker of tumor angiogenesis since the endoglin antibody binds preferentially to the activated endothelial cells that participate neovascularization." (PMID 22287958, 2012). "Importantly, classic toxicities associated with VEGF inhibition, including hypertension, proteinuria and thrombosis were not prominent, suggesting that endoglin is a selected target for debating tumor-associated angiogenesis." (PMID 22929622, 2012). "Interestingly, ENG expression strongly results in active vascular endothelial cells in tumor." (PMID 22929622, 2012). "The signal intensity after administration of endoglin-targeting microbubbles decreased with tumor size, which may reflect both reduced endoglin expression and a relative decrease in tumor vascularity, which is a typical feature of experimental subcutaneous tumors." (PMID 22837657, 2012). "Since ENG is also a well‐known marker for vascular ECs, the tumor sections were stained with anti‐CD31 (a marker for vascular ECs) and anti‐ENG antibodies." (PMID 40644310, 2025). "Inhibition of ENG expression on myCAFs not only suppressed the TGF‐β–Smad2/3 pathway and TGF‐β1 expression but also attenuated the ability of myCAF to promote primary tumor growth and metastasis." (PMID 40644310, 2025). "Endoglin, a key angiogenic target distinct from VEGFR, is upregulated in AS tumor cells following VEGFR inhibition." (PMID 40500777, 2025). "•The expression of ENG, GNG4 and ECT2 showed a significant difference between normal and tumor samples, have been identified by GEPIA analysis." (PMID 39552710, 2024). "GEPIA analysis identified three genes, ENG, GNG4, and ECT2, whose expression significantly differed between normal and tumor samples." (PMID 39552710, 2024).
tumor (continued). "Moreover, the increased expression of ENG, which plays a key role in EC functions, particularly in regulating proliferation, migration and angiogenesis, could indicate an altered endothelial state with potential impacts on tumour progression." (PMID 39768338, 2024). "Specifically, it showed a positive correlation between ENG expressions and immune lymphocytes, immuno-chemokines, immunostimulators, immunoinhibitors, MHC molecules, or immuno-receptors in most of tumor types." (PMID 39247590, 2024). "TRC105 is an IgG1 monoclonal endoglin-neutralizing antibody that prevents BMP-9 ligand binding and thereby inhibits tumor angiogenesis." (PMID 37396898, 2023). "Endoglin (CD105), a necessary glycoprotein of the TGF-β receptor complex, has been proposed as an available marker for tumor-related angiogenesis and neovascularization." (PMID 37868979, 2023). "Furthermore, generating high levels of soluble endoglin in the tumor microenvironment might impact the bio-availability of free BMP-9, which can act on the endothelial cells and regulating angiogenesis, cancer-associated fibroblasts and potential regulatory T cells and macrophages." (PMID 37396898, 2023). "Expression of VEGFC and PGF was highly correlated with the expression of endothelial markers in tumor samples, including CD31, CD34, and ENG (endoglin, a co-receptor for TGFβ)." (PMID 35600354, 2022). "An increase in endoglin expression consistent with prediction of NGS data points towards its involvement in regulating DEHP-induced angiogenesis, tumor growth, and ultimately metastasis." (PMID 35203627, 2022). "In this regard, a study evaluated the relationship between the CTC-positive status of patients with mRCC and the expression of blood tumor markers, namely cytokeratin 19 (CK19), endoglin (CD105) and CD146." (PMID 36612281, 2022). "For example, Endoglin (CD105) is a co-receptor for TGF-β and is involved in tumor angiogenesis, inflammation, and fibrogenesis." (PMID 36011021, 2022). "Endoglin, a co-receptor for tumor growth factor-β (TGF-β) in HUVECs, plays an important role in tumor angiogenesis." (PMID 35409247, 2022). "Endoglin interacts with VEGFR2 in a VEGF-dependent manner to sustain and stabilize VEGFRII on the cell surface to promote tip cell formation for tumor progression and growth." (PMID 35203627, 2022). "Endoglin participates in the neovascularization process of HCC, and is a cell proliferation marker for both vascular ECs and tumor vasculature." (PMID 33809908, 2021). "To assess the in vivo cytolytic effect of hEND-CD3/BiTE on tumor vascular endothelial cells, we measured the MVD by immunohistochemical staining of endoglin and CD34." (PMID 33995664, 2021). "The half-lives of angiogenic mRNAs, including ENG, EDN1, VEGFB and PDGFC, were reduced approximately 2-fold in Roquin2-overexpressing tumor cells compared to the control group." (PMID 34345214, 2021). "TRC105 is a chimeric IgG1 mAb that competitively blocks the binding of endoglin to its ligand bone morphogenetic protein (BMP) and inhibits tumor angiogenesis." (PMID 34381735, 2021). "Endoglin (CD105) is overexpressed in newly formed HCC microvessels, allowing tumor angiogenesis to be quantified by observing the microvascular density (MVD)." (PMID 33809908, 2021). "Approximately 30 years ago, endoglin was identified as a transforming growth factor (TGF)-β coreceptor with a crucial role in developmental biology and tumor angiogenesis." (PMID 33375670, 2020). "Treatment of RSVL reduced the ENG expression and led to the attenuation of ERK phosphorylation inhibition, resulting in increased tumor microvessel growth, which can be suppressed by PD0325901." (PMID 32326402, 2020). "Finally, the knowledge of Endoglin expression in individual immune cells might offer the opportunity to interfere with tumor promoting effects of immune cells and escape of cancers from immunosurveillance mechanisms as it has been shown for Tregs by using the anti-Endoglin antibody TRC105." (PMID 33287465, 2020).